ISG15 (ISG15 ubiquitin like modifier)
Diseases named in the same sentence as ISG15 in open-access papers (continued):
Sharing a sentence is not in itself a finding about the gene and the disease.
thyroid cancer (4 papers, 2021 to 2025). "Plasma proteomic studies have found that LCAT, GPX3, and leukotriene b4 can serve as potential biomarkers for thyroid cancer, and serum ISG15 and PLXNB2 can also serve as potential biomarkers." (PMID 40265010, 2025). "According to the analysis results of THCA samples from the TCGA database, ISG15 was highly expressed in different stages of thyroid cancer, especially ISG15 was positively increased with lymph node metastasis in patients." (PMID 37501099, 2023). "The ISG15 gene was first found in the Sino-German SimBox/Shenzhou-8 space experiment (Thyroid Cancer Cells in Space) and was detected in later proteome analyses." (PMID 35328492, 2022). "TROP2 expression was correlated with ISG15 and tumor-infiltrating immune cells in thyroid cancer." (PMID 34659576, 2021). "To explore the role of ubiquitin-like proteins (ISG15, ATG8, FAT10, NEDD8, SUMO1, UFM1, URM1 and ATG12) in thyroid cancer, we integrated the datasets (GSE33630, GSE29265 and GSE76039) and analyzed 65 NT, 69 PTC and 40 ATC samples." (PMID 37501099, 2023).
triple-negative breast carcinoma (4 papers, 2015 to 2022). An invasive breast carcinoma which is negative for expression of estrogen receptor (ER), progesterone receptor (PR), and human epidermal growth factor receptor 2 (HER2).
Arthritis (3 papers, 2015 to 2024). Inflammation of a joint. "For instance, the proteins TNFS10, SMAD3, ISG15 are annotated to increased susceptibility to induced arthritis, knee OA and abnormal bone ossification phenotypes respectively, suggesting the phenotype information complements the expression information." (PMID 25631385, 2015).
atherosclerosis (3 papers, 2022 to 2025). A disease characterized by the build-up of fatty material and calcium deposition in the arterial wall resulting in partial or complete occlusion of the arterial lumen. "A previous study identified IFIT1, IFIT2, IFIT3, and ISG15 as immune-related hub genes of atherosclerosis." (PMID 38397063, 2024). "IFIH1, IFIT1, IFIT2, IFIT3, ISG15 and OAS3 had similar expression differences to the training set and had good diagnostic abilities for atherosclerosis." (PMID 36437453, 2022). "Our study identified IFIH1, IFIT1, IFIT2, IFIT3, ISG15 and OAS3 as immune-related hub genes of atherosclerosis." (PMID 36437453, 2022).
bladder tumours (3 papers, 2006 to 2016). "Perturbations of the ISG15 pathway have been reported in tumors of the bladder, ovary, prostate, breast, and oral squamous tissue, and the downregulation of ISG15 expression has been shown to be associated with tumor progression." (PMID 27626310, 2016). "Staining of bladder tumour sections with antibody specific to ISG15 revealed specific signal for ISG15 in both cancer cells and stromal immune cells." (PMID 16641915, 2006). "In order to characterise the ISG15 expression pattern in normal urothelium and bladder tumours, we performed a series of immunohistochemical stainings." (PMID 16641915, 2006). "Importantly, a comparison of ISG15 expression across different stages of bladder tumours revealed a significant increase in ISG15 protein level with advancing tumour stage." (PMID 16641915, 2006). "Importantly, ISG15 expression did not correlate with a generalised inflammatory response, suggesting that it is specifically associated with bladder tumours." (PMID 16641915, 2006). "Moreover, the expression of several pro- and anti-inflammatory genes was unchanged between normal and bladder tumour tissue, and did not correlate with ISG15 expression." (PMID 16641915, 2006).
Cognitive impairment (3 papers, 2022 to 2024). Abnormal cognition is characterized by deficits in thinking, reasoning, or remembering. "ISG15 has a significant increase in expression between healthy controls and patients with mild cognitive impairment (MCI) and shows a decrease in patients with AD." (PMID 38890712, 2024). "If true, therapeutic strategies targeting neuronal ISG15, ISG15-specific E3 ligases, or key EV-associated miRNAs that are disrupted by ISG15 induction may prove invaluable to halting GM atrophy-related clinical progression and to mitigating or reversing cognitive impairment in patients with MS." (PMID 36261842, 2022).
diabetes (3 papers, 2022 to 2023). "In diabetes and IA, ISG15 was upregulated as a co-interacting protein of STAT1, while PTP4A3 was downregulated as a co-interacting protein of STAT1." (PMID 36561297, 2022). "Another ISG15 substrate in the DDR pathway is the tumor suppressor phosphatase and tensin homolog (PTEN), which is lost in many cancer types and also plays important roles in diabetes and autism." (PMID 37025175, 2023). "Accordingly, ISG15 and PTP4A3 may interact with STAT1 to affect diabetes and IA, though more studies are needed." (PMID 36561297, 2022).
kidney transplant (3 papers, 2020 to 2023). A surgical procedure in which one or both kidneys from a donor are implanted into a recipient. "The effects of ISG15 on lung ADC cells in vitro and in vivo are determined by cell experiments and a xenograft mouse model." (PMID 32641707, 2020). "Therefore, we speculate that Isg15 may be a new potential target for treating kidney transplant rejection." (PMID 36969159, 2023). "Importantly, ISG15 promoted ISGylation of ESRP1 and slowed the degradation of ESRP1, which demonstrated that ESRP1 and ISG15 formed a positive feedback loop and jointly suppressed EMT of lung ADC." (PMID 32641707, 2020).
leukemia (3 papers, 2016 to 2023). A malignant (clonal) hematologic disorder, involving hematopoietic stem cells and characterized by the presence of primitive or atypical myeloid or lymphoid cells in the bone marrow and the blood. "Consistent with the results in leukemia and myeloma cells, both PARP and caspase-3 were cleaved by ISG15 and USP18 in HeLa cells." (PMID 27659523, 2016).
liver fibrosis (3 papers, 2015 to 2025). "In this study, IFNα, IFNβ, ISG15, USP18, IFN-induced protein 44 (Ifi44), interferon-induced protein with tetratricopeptide repeat (Ifit) 1, Ifit2, IRF3, and IRF7 were significantly elevated in the CCl4-induced liver fibrosis model." (PMID 40260261, 2025).
lymph node metastasis (3 papers, 2021 to 2025). "Porphyromonas intermedia infection promoted growth of SCC-7 cells injected into the buccal submucosa, leading to angiogenesis, muscle invasion, lymph node metastasis, and elevated expression of Ki-67, VEGF-A, IL-6, IL-17, and ISG15." (PMID 40924302, 2025). "As seen with ISG15, UBE2L6 mRNA expression levels negatively correlated with survival in patients with cancer that had spread to the lymph nodes whereas the correlation was lost in patients without lymph node metastasis." (PMID 34556814, 2021).
myeloma (3 papers, 2016 to 2025). "Novel MM subpopulations were identified, including myeloma-activated hematopoietic stem cells and ISG15+ B cells, which correlated with survival and were validated by multiplex immunofluorescence." (PMID 40990011, 2025).
osteosarcoma (3 papers, 2023). A usually aggressive malignant bone-forming mesenchymal neoplasm, predominantly affecting adolescents and young adults. "Similar effects were observed in human osteosarcoma U2OS cells upon depletion of ISG15." (PMID 37783689, 2023). "While the role of ISG15 or MX1 in osteosarcoma is not well-studied, a recent study identified ISG15 as a potential therapeutic target in human OSA patients." (PMID 38201229, 2023). "Taken together, our data support a role of ISG15 and MX1 in canine osteosarcoma." (PMID 38201229, 2023).
periodontitis (3 papers, 2022 to 2025). An acute or chronic inflammatory process that affects the tissues that surround and support the teeth. "In gingival tissues from patients with periodontitis, an increased proportion of macrophages and elevated expression levels of IFNβ, ISG15, and IL-10 were observed." (PMID 39669221, 2025). "Single-cell analysis was conducted on the gingival tissues of patients with periodontitis, which revealed a higher proportion of macrophages in the periodontitis-diseased tissue and increased expression of IFNβ, ISG15, and IL10." (PMID 37876725, 2023). "It is also found that macrophage phenotype transitions in periodontitis involve the release of higher levels of IFNβ, ISG15, and IL10 by the anti-inflammatory M2 macrophage phenotype compared to the pro-inflammatory M1 phenotype and myeloid-derived suppressor cells (MDSCs)." (PMID 37876725, 2023). "In the periodontitis group, macrophages were observed to exhibit elevated expressions of TLR4, IFNAR1 (the receptor of IFNβ), ISG15, ITGB2 (the receptor of ISG15), IL10." (PMID 37876725, 2023). "In summary, our study found that IFNβ can inhibit the progression of chronic periodontitis and protect periodontal tissues via the induction of IL10 production through ISG15." (PMID 37876725, 2023).
Salmonella Infections (3 papers, 2014 to 2025). Infections with bacteria of the genus SALMONELLA. "Given that MSMD patients are also more susceptible to Salmonella infections, extracellular ISG15 may similarly be involved in controlling Salmonella, providing another valuable model for studying extracellular ISG15 in bacterial infections." (PMID 40719862, 2025). "This suggests that this ISG15-specific deubiquitinase is required for host resistance to Salmonella infection by contributing to the IFN signaling, which might also be relevant in other infections." (PMID 25505465, 2014).
SARS-CoV infection (3 papers, 2012 to 2022). "Noteworthy, in both cell lines we observed higher ISG15 levels after SARS-CoV-2 infection compared to SARS-CoV infection, which was in line with previously published data showing a higher interferon antagonizing capacity of SARS-CoV." (PMID 34394046, 2021). "Interestingly, immune-related pathways, such as SARS-CoV infections, ISG15 antiviral mechanism, and neutrophil degranulation, were also enriched in our results, which indicated a disruption of immune status in endometrium and inspired our interest in the immune infiltration in tissues." (PMID 35370464, 2022). "Moreover, four IRGs (ISG15, IFI44, PSME2 and CCL2) were expressed in common between the SARS-CoV infection-reinfection experiments and these 8 IRGs." (PMID 23029269, 2012). "Interestingly, the temporal expression patterns of 4 IRGs (ISG15, IFI44, PSME2 and CCL2) were similar amongst the SARS-CoV infection-reinfection experiments (50 IRGs) and this list of 8 IRGs from the adjuvanted vaccine–challenge experiments." (PMID 23029269, 2012).
vitiligo (3 papers, 2020 to 2025). Generalized well circumscribed patches of leukoderma that are generally distributed over symmetric body locations and is due to autoimmune destruction of melanocytes. "ISG15 is persuaded by type I interferons, and research have given that ISG15 is extremely expressed in vitiligo." (PMID 39872521, 2024). "The vitiligo case exhibited even higher ISG15 and PRF1, while IFNG, TNF, IL12, and IL15 levels were closer to those in healthy controls." (PMID 33384688, 2020). "In the existence of IL-15, ISG15 significantly induces the excretion of IFN-γ, contributing to the pathogenesis and progression of vitiligo, ultimately leading to melanocyte damage." (PMID 39872521, 2024).
abdominal aortic aneurysm (2 papers, 2023 to 2026). Enlargement and ballooning of the vessel that supplies arterial blood to the abdomen, pelvis and legs. "Elevated ISG15 is also observed in human and murine abdominal aortic aneurysms where antioxidant treatment mitigates its detrimental vascular effects, suggesting that ISG15 is a critical for linking interferon signalling, oxidative stress, and hypertensive vascular pathology." (PMID 41496209, 2026). "The same study found that ISG15 expression in human peripheral blood mononuclear cells positively correlated with systolic and diastolic blood pressure and with carotid intima-media thickness and also found elevated ISG15 expression in human and mouse abdominal aortic aneurysms." (PMID 37025175, 2023).
acute promyelocytic leukemia (2 papers, 2012 to 2023). An aggressive form of acute myeloid leukemia (AML), characterized by arrest of leukocyte differentiation at the promyelocyte stage, due to a specific chromosomal translocation t(15;17) in myeloid cells. "ISG15 conjugation may be similarly implicated in lung cancer and APL (acute promyelocytic leukemia)." (PMID 23109884, 2012). "In acute promyelocytic leukemia (APL), RIG-I together with STAT1 activates ISG-critical genes including ISG15, which is testified as a crucial factor to affect myeloid differentiation." (PMID 37662910, 2023).
anaplastic thyroid cancer (2 papers, 2023 to 2024). "ISG15 and ISGylation have also been shown to be increased in anaplastic thyroid cancer stem cells by flow cytometry." (PMID 39159817, 2024).
asthma (2 papers, 2021 to 2024). "Like Asthma‐3, they had high AQLQ score and low levels of ISG15/IFNγ and C3." (PMID 34962717, 2021). "Asthma‐3 had high AQLQ score and lacked control of bacterial infection by low levels of ISG15, IFNγ, and C3." (PMID 34962717, 2021).
Ataxia (2 papers, 2021 to 2024). Ataxia refers to impaired coordination of voluntary muscle movement. "Although disease severity (Scale for Assessment and Rating of Ataxia (SARA)) and change of disease severity (changes of SARA) seemed to be relevant to plasma ISG15 levels, further examination with a larger number of samples is necessary to determine the utility of ISG15 as a biomarker of SCA1." (PMID 38594382, 2024).
Cerebral calcification (2 papers, 2020 to 2022). The presence of calcium deposition within the cerebrum. "Zhang and colleagues demonstrated that patients with ISG15-deficient displayed clinical signs of enhanced IFN-α/β immunity as seen in AGS and spondyloenchondrodysplasia (SPENCD) such as cerebral calcifications (nearly 100% of patients with ISG15) and sporadic reports of seizures." (PMID 36438941, 2022). "Interestingly, ISG15-deficient patients usually present features of type 1 interferonopathy with cerebral calcifications; attributed to the role of ISG15 in controlling IFN-alpha/beta responses." (PMID 32944031, 2020).
Chlamydia infection (2 papers, 2024 to 2025). "In this paper, we described how Chlamydia infection triggered the expression of ISG15, a small molecule normally associated to type I interferon (IFN-I) signaling and control of INF-γ production." (PMID 39345209, 2024). "Our findings demonstrate a pivotal role for secreted ISG15 in the regulation of the IFN-γ-dependent defense against Chlamydia infection." (PMID 40627782, 2025). "Although we cannot exclude a role of intracellular ISG15 during Chlamydia infection, the effects described here on the dual role of ISG15 in pro- and anti-inflammatory signaling depends on secreted ISG15." (PMID 40627782, 2025). "Overall, our study strengthens the importance of ISG15 not only in the resolution of viral but also of bacterial infection and document its role of “immune brake” in the context of Chlamydia infection." (PMID 39345209, 2024). "To test the role of cGAS in ISG15 induction upon Chlamydia infection, we silenced the expression of this enzyme in HeLa cells before infection." (PMID 39345209, 2024). "The observation that ISG15 was strongly induced during Chlamydia infection prompted us to test whether it modulated Chlamydia-induced inflammation." (PMID 39345209, 2024). "ISG15 synthesis by epithelial cells attenuated their immune response to Chlamydia infection." (PMID 39345209, 2024). "Consistent with what we had observed in human cells, mouse cells KO for ISG15 displayed increased synthesis of IL6, and to a lesser extent of IL8 (KC), upon Chlamydia infection." (PMID 39345209, 2024).
colon adenocarcinoma (2 papers, 2023 to 2025). "While ISG15 mRNA is almost undetectable in normal tissues, ISG15 is elevated in different types of cancers, including colon adenocarcinoma." (PMID 36831577, 2023). "ISG15 expression was positively correlated with cancer-associated fibroblast (CAF) infiltration in COAD (colon adenocarcinoma), LGG, and THCA, while showing negative correlations in several other cancers such as BRCA, CESC, HNSC (HPV-), and mesothelioma (MESO)." (PMID 40208307, 2025).
demyelinating disease (2 papers, 2015 to 2022). A broad group of disorders that affect the myelin sheaths that cover the neurons. "In contrast, a high constitutive expression of ISG15 and PKR proteins in the spinal cord white and gray matter, which was further increased by TMEV infection, might block the spread of TMEV in C57BL/6 mice and prevent demyelinating disease based on virus persistence." (PMID 26703877, 2015).
dermatitis (2 papers, 2019 to 2024). An inflammatory process affecting the skin. "Among the generated regulatory network, STAT1, IFITM1, ISG15, and MX1 were genes associated with the IFN signaling pathway, while STAT1 and MX1 were associated with dermatitis, and STAT1 and ISG15 were associated with the inflammatory response." (PMID 30634634, 2019).
encephalitis (2 papers, 2022). An acute inflammatory process affecting the brain parenchyma. "Nevertheless at 14 dpi, BeAn-infected IFN-β-/- mice showed a stronger encephalitis and astrogliosis, higher viral load as well as higher mRNA levels of Isg15, Eif2ak2 (PKR), Tnfa, Il1b, Il10, Il12 and Ifng in the cerebrum than BeAn-infected WT mice." (PMID 35222374, 2022). "Moreover, ISG15 knockout mice displayed more severe encephalitis and excessive production of cytokines during PRV infection." (PMID 36315588, 2022).
endothelial dysfunction (2 papers, 2023 to 2026). In vascular diseases, endothelial dysfunction is a systemic pathological state of the endothelium (the inner lining of blood vessels) and can be broadly defined as an imbalance between vasodilating and vasoconstricting substances produced by (or acting on) the endothelium. "For instance, a recent report demonstrated that ISG15 mediates endothelial dysfunction and aneurysm formation in mice infused with Ang II." (PMID 37115698, 2023).
esophageal adenocarcinoma (2 papers, 2024 to 2026). A malignant tumor with glandular differentiation arising predominantly from Barrett mucosa in the lower third of the esophagus. "High expression of interferon-stimulated gene 15 (ISG15) has been associated with poor survival in patients with esophageal adenocarcinoma (EAC)." (PMID 41812883, 2026).
fibrosarcoma (2 papers, 2016 to 2021). A malignant mesenchymal fibroblastic neoplasm affecting the soft tissue and bone. "Camptothecin has been shown to induce the expression of ISG15 in human fibrosarcoma cells, which suggests that ISG15 can function as a tumor suppressor." (PMID 27626310, 2016).
fungal infection (2 papers, 2020 to 2021). "Among the upregulated proteins that function in the innate immune response, ISG15 is known as an immunomodulator that controls fungal infection and triggers the expression of proinflammatory cytokines." (PMID 34222036, 2021).
Granuloma (2 papers, 2022 to 2024). A compact, organized collection of mature mononuclear phagocytes, which may be but is not necessarily accompanied by accessory features such as necrosis. "The type I IFN cytokines (ISG15 and IFNα) expression increased in the granuloma model (3D-BSGM) but reduced in the granuloma model after α-MSH treatment (3D-BSGM + α-MSH)." (PMID 35717488, 2022).